SLC16A5 (solute carrier family 16 member 5)
Description:
Proton-linked monocarboxylate transporter. Catalyzes the rapid transport across the plasma membrane of many monocarboxylates such as lactate, pyruvate, branched-chain oxo acids derived from leucine, valine and isoleucine, and the ketone bodies acetoacetate, beta-hydroxybutyrate and acetate (By similarity).
Synonyms: MCT5; MCT6
Tractability: Antibody: its Gene Ontology location is reachable by antibodies, with high confidence; UniProt places it where antibodies can reach, with medium confidence; UniProt predicts a signal peptide or a membrane-spanning region. PROTAC: ubiquitination databases record sites on it.
Safety:
Unwanted effects reported when the protein is acted on. In parentheses: how it was acted on, where the effect was seen, and who reports it.
ototoxicity (source: ClinPGx)
Gene: Protein-coding gene on chromosome 17 (75,077,226 to 75,106,162, forward strand). Ensembl gene ENSG00000170190.
Subcellular location: Cell membrane
Gene Ontology:
Molecular function: protein binding; monocarboxylic acid transmembrane transporter activity; transmembrane transporter activity
Biological process: monocarboxylic acid transport; transmembrane transport
Cellular component: basolateral plasma membrane; membrane; plasma membrane
Genetic constraint (gnomAD): Loss-of-function variants: 29 observed, 35.15 expected, observed/expected ratio (o/e) 0.83, 90% interval 0.61 to 1.12. The upper end of that interval is the gene's LOEUF score, 1.12, which puts it in group 4 of 6, group 1 being the genes least tolerant of losing a copy. Missense variants: 596 observed, 692.11 expected, observed/expected ratio (o/e) 0.86, 90% interval 0.8 to 0.92. Synonymous variants: 242 observed, 290.24 expected, observed/expected ratio (o/e) 0.83, 90% interval 0.75 to 0.93.
Homologues: Orthologues: chimpanzee SLC16A5 (99% identical), macaque SLC16A5 (86% identical), dog SLC16A5 (74% identical), rabbit SLC16A5 (70% identical), pig SLC16A5 (70% identical), rat Slc16a5 (62% identical), guinea pig SLC16A5 (59% identical), tropical clawed frog slc16a5 (47% identical), zebrafish slc16a5b (42% identical), zebrafish slc16a5a (42% identical), Drosophila melanogaster Mct1 (25% identical), Drosophila melanogaster CG13907 (24% identical), and 12 more. Paralogues in human: SLC16A8 (35% identical), SLC16A3 (33% identical), SLC16A7 (28% identical), SLC16A6 (27% identical), SLC16A1 (26% identical), SLC16A12 (26% identical), SLC16A11 (25% identical), SLC16A13 (23% identical), SLC16A14 (22% identical), SLC16A4 (22% identical), SLC16A9 (21% identical), SLC16A10 (20% identical), and 1 more.
Diseases named in the same sentence as SLC16A5 in open-access papers:
SLC16A5 is named in the same sentence as 17 diseases in open-access papers, as found by Europe PMC text mining. Sharing a sentence is not in itself a finding about the gene and the disease. The quoted sentences say what the papers report.
breast carcinoma (1 paper, 2021). "Next, we further evaluated the expression of SLC16A5 in 166 breast cancer tissues and 40 normal tissues by immunohistochemical staining." (PMID 33754068, 2021). "In addition, immunohistochemical analysis confirmed that high expression of SLC16A5 was associated with larger tumor size, lymph node metastasis, and advanced TNM stage in breast cancer." (PMID 33754068, 2021). "The Kaplan-Meier analysis revealed that high expression of SLC16A5 was correlated with poor prognosis of both OS and PFS in HER2-positive breast cancer patients (p < 0.05)." (PMID 33754068, 2021).
Cachexia (1 paper, 2022). Severe weight loss, wasting of muscle, loss of appetite, and general debility related to a chronic disease. "Furthermore, we detected the mRNA expression of lactate transporters Slc16a1 (in muscle), Slc16a5, and Slc16a7 (in liver) and found that the levels of all three lactate transporters were upregulated in the cachexia group compared with the NC group, and the 2-DG treatment reversed this change." (PMID 36230949, 2022).
colorectal cancer (1 paper, 2022). A primary or metastatic malignant neoplasm that affects the colon or rectum. "For example, in individuals with colorectal cancer, increased SLC2A3 expression was related with decreased overall survival and disease-free survival, while increased SLC16A5 expression predicted increased survival in prostate cancer patients." (PMID 35518353, 2022).
dyslipidemia (1 paper, 2021). "However, there are reports on six of Slc genes (Slc2a10, Slc5A1, Slc5a9, Slc6A14, Slc16A5, Slc25A24) in metabolic diseases including obesity, dyslipidemia, NAFLD, and T2DM." (PMID 34659115, 2021).
hearing loss (1 paper, 2018). "As well, a statistical trend between rs4788863 in SLC16A5 gene and hearing loss under a dominant genetic model hypothesis was shown (P=0.07)." (PMID 30112115, 2018). "The rs4788863 in SLC16A5 has also been correlated with hearing loss in adults." (PMID 30112115, 2018).
Hypertension (1 paper, 2011). The presence of chronic increased pressure in the systemic arterial system. "In addition, Cyp4a14 and slc16a5, as the top 30 fold change genes induced by 24-h fasting, have been reported to be involved in hypertension and the disposition of various drugs respectively." (PMID 22096593, 2011).
pancreatic cancer (1 paper, 2020). "The boxplot of the RNA-Seq expression in 179 pancreatic cancer vs 171 normal pancreas samples demonstrated that SLC16A1, SLC16A2, SLC16A3, SLC16A4, SLC16A5 and SLC16A13 were increased with statistical meaning." (PMID 32355273, 2020).
prostate tumors (1 paper, 2018). "Analysis of these genes in patient samples from the TGCA dataset using the MethHC database (methhc.mbc.nctu.edu.tw) confirmed significant hypermethylation of the DKK3, PTGS2, SLC16A5, HFE, and CYP27A1 promoters in prostate tumors, compared to normal prostate." (PMID 29843383, 2018).
testicular cancer (1 paper, 2021). A primary or metastatic malignant neoplasm that affects the testis. "A multicenter study found that SLC16A5 gene mutation was associated with adverse reactions to platinum-based drugs in testicular cancer patients, which provided a reference for the mechanism of adverse reactions in testicular cancer." (PMID 34424811, 2021).
cancer (4 papers, 2014 to 2022). A tumor composed of atypical neoplastic, often pleomorphic cells that invade other tissues. "Others like GRASP, HEMK1, RARB and SLC16A5 were methylated mostly in histologically detectable cancer and may represent later events." (PMID 25548652, 2014). "The DCGs, including GART, TGFB1, ITGA2, SLC16A5, SOX9, and MMP7, were investigated across 12 cancer types." (PMID 29843204, 2019). "A review of the literature revealed that aberrant expression of CKMT1A, GCNT1, NCALD, NFKBIB, NOMO3/Nodal, SLC16A5, or TRPV2 was correlated with cancer." (PMID 31363162, 2019).
infection (1 paper, 2019). The state of being infected such as from the introduction of a foreign agent such as serum, vaccine, antigenic substance or organism. "Notably, SLC16A5 was consistently upregulated to the highest extent across all groups, regardless of dexamethasone treatment or time post-infection." (PMID 31635289, 2019). "Of these, a notable top upregulated cluster is identified, containing only one gene, solute carrier family 16 member 5 (SLC16A5; ENSOCUG00000016231), which was highly upregulated across all five comparisons, irrespective of dexamethasone treatment and time post-infection." (PMID 31635289, 2019).
tumor (1 paper, 2021). "SLC16A5 is a member of the monocarboxylic acid transporter family which plays an important regulatory role in tumor cell energy metabolism and tumor microenvironment." (PMID 33754068, 2021). "The results showed that SLC16A5 expression was significantly higher in tumor tissues than that in adjacent tissues (chi-square test, p < 0.01)." (PMID 33754068, 2021).
SLC16A5 also shares sentences with these, for which no sentence is quoted: kidney cancer (1 paper); metabolic disease (1); Obesity (1); prostate carcinoma (1); uterine diseases (1).